CD34 (CD34 molecule)
Diseases named in the same sentence as CD34 in open-access papers (continued):
Sharing a sentence is not in itself a finding about the gene and the disease.
colon carcinoma (30 papers, 1999 to 2026). "Following the administration of oncolytic measles viruses encoding s4-1BBL-TriXVIII, significant tumor regression and prolonged survival were achieved in a CD34+ cell-humanized colon cancer model." (PMID 41328355, 2026). "Here, the immune gene CD34/CD276 with different m6A peak was obtained by m6A sequencing (MeRIP-seq) of colon cancer (CRC)clinical samples and combined with MsIgDB database, which was used to perform cluster analysis on TCGA-COAD level 3 data." (PMID 34307389, 2021). "In this study, primary human MCs were generated from CD34+ progenitor cells and a 3D coculture model was developed to study the interplay between colon cancer cells and MCs." (PMID 30987352, 2019). "In this study, primary MCs from human peripheral CD34+ stem cells were generated and an in vitro 3D coculture model was developed to study the MC—colon cancer interaction." (PMID 30987352, 2019). "First, CD34-immunostained whole slides of colon carcinoma samples were scanned and blood vessels were extracted by image segmentation." (PMID 26061817, 2015). "In the present study, the attempts were undertaken to obtain monocytes from bone marrow (BM) haematopoietic CD34+ stem cells of patients with colon cancer and to determine their immunophenotype and some functional activities." (PMID 23180014, 2013). "The present observations clearly demonstrate the feasibility of in vitro generation of monocytes from BM CD34+ haematopoietic stem cells of colon cancer patients." (PMID 23180014, 2013). "Colon cancer has also been shown to contain endothelial cells which co-express both CD34 and Prox-1, which may suggest that the co-expression of these lineage markers is a result of tumorigenesis in endothelial tumors." (PMID 37046832, 2023). "Compared with the CRC group, the ZS40-H, ZS40-L, BLA, and SD groups had decreased levels of colon cancer marker proteins CD34 and CD117, and the number of abnormal colonic lesions observed by colon histology decreased, while the ZS40-H group showed excellent results." (PMID 36225358, 2022). "Immunocytochemistry showed that CD34+ hMVECs in vitro have filopodia-like extensions that are positive for CD34, similarly to the extensions of tip cells in sprouting vascular fronts in mouse retina and in human colon carcinoma in vivo." (PMID 29951828, 2018). "Therefore, immunohistochemical analysis was used to detect the expression of vimentin, Ki-67, and CD34 in colon cancer xenografts." (PMID 28358024, 2017). "In addition, serial tissue sections with immunohistochemical staining analyses further confirmed that VASH1 and CD34 molecules were co-expressed in blood endothelial cells in colon cancer tissues." (PMID 25797264, 2015). "However, significant correlation and co-expression between stromal VASH1 and microvessel density marker CD34 were found in colon cancer tissues." (PMID 25797264, 2015). "To further investigate the functional effect and correlation of VASH1 and CD34 involved in the active angiogenesis in colon cancer, we determined whether VASH1 expression was co-localized with CD34 in endothelial cells in cancer stroma." (PMID 25797264, 2015). "FXR-KO mice exhibited elevated colon cancer markers (β-catenin, LGR5, CD44, CD34, and cyclin D1) under LPS, underscoring the pivotal role of FXR in inhibiting the development of colon tumorigenesis." (PMID 38069256, 2023). "Using H&E staining and CD34/PAS double-staining, VM was distinguished by channels lined with colon cancer cells instead of shuttle-like endothelial cells." (PMID 26266404, 2015). "Vascularity was estimated by CD34 staining, and TSP-2(–)/VEGF-189(+) colon cancers showed significantly increased vessel counts and density in the stroma (P < 0.0001)." (PMID 9888480, 1999). "Here we found that PD-L1 expression in the normal lung tissue was low or none, whereas a significant percentage of CD34+ blood vessels exhibited high PD-L1 expression in lung adenocarcinoma tissue, colon cancer and renal cancer." (PMID 32366856, 2020).
colon carcinoma (continued). "The short-term competition assay showed that SW480, a colon cancer cell line, did not inhibit CD34+ HSC engraftment." (PMID 30089913, 2019). "Consistent with the PDX analysis, we found enhanced staining for CD31, CD105, CD34 (mature and immature blood vessel marker) and PDGFRB in colon tumors from p38αΔUb mice, suggesting that p38α downregulation stimulated tumor vessel density and perivascular cell recruitment." (PMID 31296856, 2019). "Finally, the expression of Snail1, CD34 and CD31 as angiogenic marker, was analyzed by IHC in a series of 53 colon cancer patients." (PMID 30250018, 2018). "In addition, we investigated the expression levels of the other well-known angiogenic molecules CD34 and VEGF-A, as well as lymphoangiogenenic molecules D2-40 and VEGF-C in colon cancer tissues and paracancerous normal tissues." (PMID 25797264, 2015). "In addition, expression levels of CD34, D2-40, VEGF-A and VEGF-C in colon cancer tissues were significantly higher than those in paracancerous normal tissues." (PMID 25797264, 2015). "Furthermore, box plot and linear correlation analyses demonstrated that there was a significant correlation between stroma VASH1 and CD34, a key microvessel density (MVD) marker, in colon cancer tissues." (PMID 25797264, 2015).
endothelial dysfunction (30 papers, 2008 to 2025). In vascular diseases, endothelial dysfunction is a systemic pathological state of the endothelium (the inner lining of blood vessels) and can be broadly defined as an imbalance between vasodilating and vasoconstricting substances produced by (or acting on) the endothelium. "The aim of our study was to find out whether endothelial dysfunction is associated with the number of CD34+ cells and TNF-α levels in patients with advanced HF of ischemic and non-ischemic origin after stimulation with G-CSF." (PMID 36005445, 2022). "Therefore, maternal endothelial dysfunction and CD34+ alterations associated with PE may contribute to the decreased plasma levels of VEGFR-2 associated with this condition." (PMID 22428059, 2012). "After alcohol cessation Lyve1 and Stab2 expression returned to control levels, but in contrast, Icam1, Vcam1, and Cd34 stayed elevated or further increased suggesting that endothelial dysfunction persists after alcohol cessation." (PMID 40288442, 2025). "As we know from prior study that physical activity, even for a short duration, can improve endothelial function and CD34+ circulating progenitor cells in patients with endothelial dysfunction." (PMID 32493344, 2020). "Our results indicate that CPAP can potentially improve endothelial dysfunction as evidenced by CD34+ cell data and AS data." (PMID 31113468, 2019). "Although there have been many different markers of inflammation used to look at endothelial dysfunction, cell-based biomarker such as hematopoietic progenitor cells CD34+ cells to assess endothelial function and treat cardiovascular diseases has been widely used in various clinical scenarios." (PMID 31113468, 2019). "A higher percentage of CD34+ CXCR4+ cells may which help by homing-in on the kidney vasculature to repair the endothelial dysfunction present and thereby help prevent progressive kidney damage." (PMID 29724198, 2018). "miR-222 expression correlates with endothelial dysfunction, vascular injury and CD34+ cell levels." (PMID 30347712, 2018). "The circulating CD34 progenitor cells and CD34-positive vascular endothelial growth factor receptor-2-positive endothelial progenitor cells, which are correlated with vascular calcification, worsen the endothelial dysfunction." (PMID 28286758, 2017). "Consequently, the results of the present study support the conclusion that chronic smoking affects the level of CD34 + progenitor cells before manifestation of endothelial dysfunction in healthy young women." (PMID 20509965, 2010). "Therefore, we examined the effect of OXA on endothelial cells and found no detectable impact on genes associated with endothelial dysfunction and vascular injury, including Fabp4, Pcdh17, Esm1, and Cd34." (PMID 37697332, 2023). "However, the role of EPCs CD45+CD34+KDR+ within endothelial dysfunction may be still under debate, since converse results have been obtained, probably due to differences in the design to explore this target." (PMID 36831250, 2023). "Furthermore, other parameters that may explain the interaction of CD34+ cell number and endothelial dysfunction, such as flow-mediated dilation, redox status, and oxidative stress determination, were not evaluated." (PMID 35885020, 2022). "The aim of our study was to find out whether endothelial dysfunction is associated with the number of CD34+ cells and TNF-α levels in patients with ischemic and non-ischemic HF after stimulation with granulocyte colony-stimulating factor (G-CSF)." (PMID 36005445, 2022). "Thus, the depletion of CD34+/AC133+/CD31+/CD45dim cells is predictive of endothelial dysfunction." (PMID 30321232, 2018). "Besides increasing exercise capacity in these patients, physical exercise also improves endothelial dysfunction and decreases certain inflammatory mediators, such as C-reactive protein, superoxide dismutase, 8-isoprostane, and CD34/KDR+ endothelial progenitor cell count." (PMID 24616817, 2014).
endothelial dysfunction (continued). "Based on our observation and previous studies, we suggested that the upregulated CD34 and decreased GSH result in an inflammatory and oxidative microenvironment in the blood vessels, and eventually lead to endothelial dysfunction." (PMID 38196515, 2023). "Interestingly, healthy smokers showed similar endothelial dysfunction in the brachial artery than COPD patients, but the number of circulating CD45+CD34+CD133+ was significantly increased compared to COPD patients and unrelated to the endothelial function." (PMID 25171153, 2014). "Based on literature and our past CD34+ve cell based studies, it is likely that circulating CD34+ EPC number, function and mRNA expression can act as a robust cellular biomarker that is more reliable than serum-based biomarkers for monitoring endothelial dysfunction in type 2 diabetes." (PMID 32493344, 2020).
acute promyelocytic leukemia (29 papers, 2008 to 2025). An aggressive form of acute myeloid leukemia (AML), characterized by arrest of leukocyte differentiation at the promyelocyte stage, due to a specific chromosomal translocation t(15;17) in myeloid cells. "For example, acute promyelocytic leukemia (APL) exhibits a characteristic immunophenotype (CD34−, HLA-DR−, CD117+, CD15−) that can prompt PML::RARA gene fusion evaluation and consequent management until the molecular result is available." (PMID 37366878, 2023). "The acute promyelocytic leukemia‐like phenotype CD34(−)/HLA‐DR(−)/MPO(str+) was present in nearly half the patients (48%) and beneficially influenced RFS and OS." (PMID 36808479, 2023). "Enforced expression of miR-125a-5p also induced granulocytic differentiation in the human acute promyelocytic leukemia cell line NB4 as well as in primary normal CD34+-HPCs, as assessed by a remarkable increase in the percentage of CD11b+-positive cells." (PMID 31523391, 2019). "Here, the mechanism of TSY-1 on cellular Telomerase activity was further investigated using HL60, a promyelocytic leukemia cell line, normal peripheral blood mononuclear cells, and CD34+ hematopoietic stem cells derived from umbilical cord blood." (PMID 28002788, 2017). "CD2+, CD34+, and CD56+ immunophenotypes are associated with poor prognoses of acute promyelocytic leukemia (APL)." (PMID 25045197, 2014). "At the time of initial diagnosis, the child’s bone marrow was evaluated through cytomorphometry and flow cytometric immunophenotyping, revealing an atypical immunophenotype consistent with acute promyelocytic leukemia (APL) (CD34-/HLA-DR-/CD45-CD117)." (PMID 40951356, 2025). "Interestingly, MALNC is dynamically expressed in normal myelopoiesis, with minimal levels in immature CD34+ cells, peaking at the promyelocytic stage, and declining during granulocytic maturation, a pattern also observed during differentiation of promyelocytic leukemia cell lines." (PMID 40849353, 2025). "According to the analysis of myeloid blast population, nearly half of NPM1mut patients show an acute promyelocytic leukemia (APL)-like antigen expression feature represented by CD34(−)/HLA-DR(−)/MPO(str+)." (PMID 34238278, 2021). "MiR-107 has been reported to be downregulated in acute promyelocytic leukemia (APL) blasts as compared with normal promyelocytes differentiated in vitro from CD34+ progenitors, and its expression level was upregulated after cells had been treated with ATRA." (PMID 33153128, 2020). "We found miR-143 to be upregulated during granulocytic differentiation of primary human CD34+ stem/progenitor cells (HSPCs), primary acute promyelocytic leukemia (APL) patient samples, and various AML cell lines." (PMID 30050105, 2018). "Ectopic expression of miR-125a-5p also promoted granulocytic differentiation in human acute promyelocytic leukemia NB4 cells, as well as in naïve human primary CD34+-hematopoietic progenitor/stem cells." (PMID 31523391, 2019). "Kikushige and Miyamoto reported that TIM-3 expression increased in CD34+/CD38- LSCs and blast cells in most AML patients, except for acute promyelocytic leukemia (M3), normal HSCs, and normal progenitors." (PMID 27506934, 2016). "TIM-3 has been identified as a marker of LSCs with lack of expression on normal CD34+CD38- HSCs but not CD34+CD38- LSCs in most types of AML except for acute promyelocytic leukemia (M3)." (PMID 36605213, 2022). "Furthermore, RT-PCR also detected CCDC103 expression in human myeloid cells and myeloid progenitors, whole-blood-derived CD34+/CD38− cells, whole cord blood and in the promyelocytic leukemia HL-60 cell line." (PMID 34028558, 2021). "Notably, a significant subset of NPM1-mutated AML cases also exhibit HLA-DR negativity, classifying them as “double-negative”, and mimicking, therefore, the CD34− HLA-DR− immunophenotype of acute promyelocytic leukemia (APL)." (PMID 39457595, 2024).
acute promyelocytic leukemia (continued). "In an in vivo experimental model of acute promyelocytic leukemia (APL), specifically the PML/RARα model, green tea was found to increase the levels of reactive oxygen species (ROS) within bone marrow Gr1+ cells, simultaneously decreasing the number of CD34+ and CD117+ cells." (PMID 37513933, 2023). "We collected available DNase I footprint datasets in six different human cell-types from three healthy donors (CD34+ (mobilized), CD20+ and Th1 cells), transformed B-lymphocytes (GM12865) and two cancer cell-types where c-Myb is upregulated: erythroleukaemia (K562) and promyelocytic leukaemia (NB4)." (PMID 26208222, 2015). "In an acute promyelocytic leukemia (APL) model (PML/RARα), green tea treatment reduced blast percentages (CD34 and/or CD117) in the bone marrow and spleen possibly through the induction of apoptosis and reduction in the CXCR4/HIF-1α signaling pathway in response to a decrease in ROS levels." (PMID 37513933, 2023). "The combined use of CD34 and HLA-DR was more helpful in distinguishing Acute Promyelocytic Leukemia (APL) from non-Acute Promyelocytic Leukemia (non-APL) none of the eighteen cases of APL were positive for both CD34 and HLA-DR whereas 64.77% of non-APL (83%) were positive for both CD34 and HLA-DR." (PMID 31086535, 2019). "In the training cohort, 24 AML (non-acute promyelocytic leukemia, APL) patients were enrolled in Peking University People’s Hospital and tested for ECHDC3 in enriched CD34+ cells at diagnosis." (PMID 36172164, 2022). "Originally, L-IC have been identified as CD34+CD38− cells (i.e., by the combination of CD34 expression and the lack of CD38 and other markers of advanced commitment) in most samples of AML patients but with the notable exception of patients suffering from acute promyelocytic leukemia (APL)." (PMID 26880987, 2016).
anemia (29 papers, 2010 to 2025). A reduction in the number of red blood cells, the amount of hemoglobin, and/or the volume of packed red blood cells. "NSGS mice developed severe anemia between 8 and 16 weeks after CD34+ cell transplantation, as observed by pallor, weight loss and low bone marrow cellularity." (PMID 35804867, 2022). "In PMF, male gender, older age, and MPL mutation were independently correlated with reduced CD34+CXCR4+ cells and associated with a briefer interval to develop severe anemia, large splenomegaly, thrombocytopenia, leukopenia, elevated CD34+ blood cells, blast transformation, and death." (PMID 34771488, 2021). "In the univariate Cox analysis, increasing risk category of all scores, degree of anemia, higher percentage of BM blasts, higher number of CD34+ cells and their myeloid fractions besides increasing number of phenotypic abnormalities detected were significantly associated with a shorter survival." (PMID 24324660, 2013). "To study the role of HSPA9 in regulating erythroid maturation, we knocked down the expression of HSPA9 in human CD34+ hematopoietic progenitor cells grown in erythroid differentiation media to explore the mechanism of anemia observed in del(5q) MDS patients." (PMID 38508444, 2024). "It was reported that NSG-SGM3 mice develop anemia upon humanization with cord blood CD34+ HSCs which shortens the lifespan of humanized NSG-SGM3 mice and poses a challenge for immuno-oncology research that requires a long study window." (PMID 37868989, 2023). "We also detected improved erythroid differentiation upon DDIT3 knockdown in CD34+ cells of four additional MDS cases showing anemia." (PMID 36494342, 2022). "In conclusion, we found that, in PMF patients, the CXCR4 expression on CD34+ cells was strongly correlated with severe anemia, thrombocytopenia, leukopenia, increased concentration of blood CD34+ cells, larger spleen size, and severe BM fibrosis." (PMID 34771488, 2021). "CD34+ cells were collected from anemia patients and treated with ZFN-L/R and Donor plasmid, respectively or together." (PMID 29554925, 2018). "The number of CD133+CD34+ and CD133-CD34+ cells circulating in CB was higher in preterm infants who developed RDS, BPD and NEC, whereas anemia was associated only with a higher number of CD133-CD34+ CB cells." (PMID 22985188, 2012). "Therefore, further studies into the underlying mechanisms of CD34 and CD38 expression in inflammatory-related anemia are needed to fully understand their potential usefulness as indicators of anemia severity and associated pathologies." (PMID 37240288, 2023). "For CD34 and CD38, AUC was moderately high in the tested model, anemic vs. non-anemic (AUC = 0.600, sensitivity 76.8%, specificity 50.0% for CD34, and AUC = 0.657, sensitivity 76.8%, specificity 57.8% for CD38), which indicates their moderate diagnostic utility in patients with anemia." (PMID 37240288, 2023). "Both anemia and oxidative stress are known to promote the release of pro-inflammatory cytokines and reactive oxygen species, which can activate immune cells and potentially induce the expression of CD34 and CD38." (PMID 37240288, 2023). "However, the OR values for CD34 (OR = 3.264, 95%Cl 1.263–8.747) and CD38 (OR = 4.398, 95%Cl 1.701–11.906) suggested a significantly higher probability of developing anemia in patients with cut-off values >19.1 ng/mL for CD34 and >1.4 ng/mL for CD38." (PMID 37240288, 2023). "Although the available literature on CD34 and CD38 involvement in anemia is limited, and the exact mechanisms underlying the observed differences in CD34 and CD38 levels are not fully understood, the engagement of several factors may already be identified." (PMID 37240288, 2023). "Moreover, DDIT3 knockdown in CD34+ cells from MDS patients with anemia is able to restore erythropoiesis." (PMID 36494342, 2022).